AGAP5 (ArfGAP with GTPase domain, ankyrin repeat and PH domain 5)
Description:
Putative GTPase-activating protein.
Synonyms: CTGLF2; Em:AC073389.1
Tractability: No criterion of Open Targets' tractability assessment is met for any kind of drug.
Gene: Protein-coding gene on chromosome 10 (73,674,287 to 73,698,109, reverse strand). Ensembl gene ENSG00000172650.
Gene Ontology:
Molecular function: GTPase activator activity; GTPase activity
Genetic constraint (gnomAD): Loss-of-function variants: 7 observed, 18.35 expected, observed/expected ratio (o/e) 0.38, 90% interval 0.22 to 0.72. The synonymous counts are far from expectation, so gnomAD's model fits this gene poorly and the ratio says little. Missense variants: 279 observed, 655.02 expected, observed/expected ratio (o/e) 0.43, 90% interval 0.38 to 0.47. Synonymous variants: 108 observed, 240.54 expected, observed/expected ratio (o/e) 0.45, 90% interval 0.38 to 0.53.
Homologues: Paralogues in human: AGAP4 (97% identical), AGAP6 (96% identical), AGAP9 (91% identical), AGAP1 (63% identical), AGAP3 (48% identical), AGAP2 (43% identical), ACAP3 (19% identical), ACAP2 (18% identical), ASAP2 (17% identical), ASAP1 (17% identical), ACAP1 (17% identical), ARAP2 (16% identical), and 16 more.
Diseases named in the same sentence as AGAP5 in open-access papers:
AGAP5 is named in the same sentence as 2 diseases in open-access papers, as found by Europe PMC text mining. Sharing a sentence is not in itself a finding about the gene and the disease.
AGAP5 shares sentences with these, for which no sentence is quoted: diabetes (1 paper); Stroke (1).